MRPL2 (mitochondrial ribosomal protein L2)
Synonyms: CGI-22; MRP-L14; RPML14; uL2m
Tractability: Small molecule: a structure with a bound ligand is known. PROTAC: ubiquitination databases record sites on it; its protein half-life has been measured.
Gene: Protein-coding gene on chromosome 6 (43,054,029 to 43,059,449, reverse strand). Ensembl gene ENSG00000112651.
Subcellular location: Mitochondrion
Subcellular location (Human Protein Atlas): Mitochondria; Nucleoplasm
Pathways (Reactome):
Metabolism of proteins: Mitochondrial ribosome-associated quality control; Mitochondrial translation elongation; Mitochondrial translation initiation; Mitochondrial translation termination
Gene Ontology:
Molecular function: RNA binding; structural constituent of ribosome
Biological process: mitochondrial translation; translation
Cellular component: mitochondrial large ribosomal subunit; mitochondrion; mitochondrial inner membrane; ribosome
Genetic constraint (gnomAD): Loss-of-function variants: 27 observed, 33.85 expected, observed/expected ratio (o/e) 0.8, 90% interval 0.59 to 1.1. The upper end of that interval is the gene's LOEUF score, 1.1, which puts it in group 4 of 6, group 1 being the genes least tolerant of losing a copy. Missense variants: 366 observed, 393.37 expected, observed/expected ratio (o/e) 0.93, 90% interval 0.85 to 1.01. Synonymous variants: 133 observed, 140.97 expected, observed/expected ratio (o/e) 0.94, 90% interval 0.82 to 1.09.
Homologues: Orthologues: chimpanzee MRPL2 (99% identical), dog MRPL2 (89% identical), guinea pig MRPL2 (88% identical), rabbit MRPL2 (87% identical), pig MRPL2 (87% identical), mouse Mrpl2 (84% identical), rat Mrpl2 (84% identical), zebrafish mrpl2 (67% identical), tropical clawed frog mrpl2 (45% identical), Drosophila melanogaster mRpL2 (40% identical), Caenorhabditis elegans mrpl-2 (33% identical). Paralogues in human: RPL8 (19% identical).
Diseases named in the same sentence as MRPL2 in open-access papers:
MRPL2 is named in the same sentence as 7 diseases in open-access papers, as found by Europe PMC text mining. Sharing a sentence is not in itself a finding about the gene and the disease. The quoted sentences say what the papers report.
Blindness (1 paper, 2021). Blindness is the condition of lacking visual perception defined as a profound reduction in visual perception. "For example, MRPL2, MRPL14, MRPS10, MRPS18A, and MRPS18B are candidate genes for spinocerebellar ataxia with blindness and deafness." (PMID 34987545, 2021).
hyperopia (1 paper, 2017). A refractive error in which rays of light entering the eye parallel to the optic axis are brought to a focus behind the retina, as a result of the eyeball being too short from front to back. "It must be noted, however, that two of the mitochondrial ribosomal genes (MRPS21 and MRPL2) were also up-regulated in late hyperopia." (PMID 28852117, 2017).
infection (2 papers, 2020 to 2022). The state of being infected such as from the introduction of a foreign agent such as serum, vaccine, antigenic substance or organism. "We find that mrpl-2(osa3) mutants lived longer and survived better during pathogen infection depending on the diet they were fed." (PMID 33338044, 2020). "Next, we examined the effect of diet on the ability of mrpl-2(osa3) animals to survive infection with the opportunistic pathogen Pseudomonas aeruginosa." (PMID 33338044, 2020). "Accordingly, mrpl-2(osa3) animals survived significantly longer than wild-type animals during infection with P. aeruginosa if they were previously fed a diet of E. coli OP50." (PMID 33338044, 2020). "We find that the mrpl-2 mutant exhibits extended lifespan and increased survival during pathogen infection." (PMID 33338044, 2020). "In response to infection, in male mice, the TACC2, BUB1B, ATP5MC3, and MYO1E, and in female mice, the CAP1, MRPL2, COX5A, KLHL21, PDIA6, TSPO, and USP14 had direct interaction with TP-53." (PMID 35844510, 2022).
cardiac diseases (1 paper, 2025). "Dysregulationof MRPL2 expression has been linked to the pathogenesis of cardiacdiseases." (PMID 39841981, 2025). "We identifiedeight proteins exclusive to the exposure group PR, with leucine-richsingle-pass membrane protein 2 (LSMEM2) and MRPL2 showing significantassociations with cardiac diseases." (PMID 39841981, 2025).
MRPL2 also shares sentences with these, for which no sentence is quoted: deafness (1 paper); heart failure (1); spinocerebellar ataxia (1).